UHRF1 (ubiquitin like with PHD and ring finger domains 1)
Diseases named in the same sentence as UHRF1 in open-access papers (continued):
Sharing a sentence is not in itself a finding about the gene and the disease.
cancer (continued). "UHRF1 enhances the invasiveness of osteosarcoma cancer cells by downregulating the tumor suppressor E-cadherin and promoting epithelial–mesenchymal transition (EMT), a process pivotal for cancer cell dissemination." (PMID 39051184, 2024). "The DiPRO1 interaction partners UHRF1 and TIF1B have been proposed as targets for cancer therapy." (PMID 39009887, 2024). "Research further suggests that targeting UHRF1, alongside inhibiting the KRAS pathway and its downstream effector PI3K, could synergistically curb cancer cell growth." (PMID 39051184, 2024). "However, further studies are needed to investigate the role of UHRF1 in the SIRT3/SOD2-Akt signaling pathway, which regulates various critical cellular processes required for cancer cell survival." (PMID 37630248, 2023). "Indeed, the SRA (SET and RING-associated) domain of UHRF1 recognizes hemi-methylated DNA generated during DNA replication which allow UHRF1 to recruit DNMT1 in order to methylate the newly synthesized DNA strand, resulting in silencing of many TSGs in cancer." (PMID 35566130, 2022). "Ubiquitin-like with PHD and RING finger domain 1 (UHRF1) is a molecule usually overexpressed in cancer, which is normally responsible for the regulation of DNA methylation." (PMID 35345849, 2022). "The aim of the present study was to extract BSO from black seeds sourced from the local market of Al-Qassim, Saudi Arabia, to determine its content of TQ and to investigate its inhibitory effects on the expression of UHRF1, DNMT1 and HDAC1 and the related events in several cancer cells." (PMID 35566130, 2022). "At present, no mechanism can explain why TQ selectively induces UHRF1 degradation in cancer cells without affecting its expression levels in normal cells." (PMID 33922029, 2021). "Despite being an attractive drug target, no highly potent UHRF1-targeting cancer therapeutics or chemical probes have been developed to date." (PMID 33441849, 2021). "Given these important roles, compounds that target UHRF1-TTD activities could be useful chemical probes for studying UHRF1 functions and determining which domain contributes to cancer." (PMID 33441849, 2021). "Thus, understanding the role of the UHRF1/DNMT1/HDAC1/G9a complex in reading the epigenetic marks (DNA methylation and histone marks) in cancer will allow the development of a new generation of multitarget epidrugs." (PMID 33922029, 2021). "Collectively, these data further support a model of UHRF1-dependent DNA methylation maintenance in cancer cells that does not involve histone- or non-histone methyllysine-driven interactions through the UHRF1 TTD." (PMID 33097091, 2020). "The contribution of this methyllysine-driven interaction to cancer cell DNA methylation maintenance through UHRF1 has not been considered." (PMID 33097091, 2020). "Furthermore, we provide evidence for widespread co-expression of UHRF1 and DNMT1 and activated MEK/ERK pathway as a driving force for frequent UHRF1/DNMT1 overexpression in cancers." (PMID 30696879, 2019). "Taken together, these data provide compelling evidence that 2i broadly inhibits UHRF1 and DNMT1 expression in cancer cells by inhibition of the MEK/ERK pathway, which is broadly required for elevated transcription of both UHRF1 and DNMT1 in various cancer cells." (PMID 30696879, 2019). "In fact, by three different approaches, the co-expression score of UHRF1 and DNMT1 is higher than that of DNMT1 and DNMT3A, which was previously proposed to be coordinately co-expressed in order to maintain DNA methylation homeostasis in cancer cells." (PMID 30696879, 2019). "Despite such credentialing of UHRF1 as a target for cancer therapy, to date there have been no published attempts to our knowledge to identify small molecule UHRF1 inhibitors, in part due to a lack of robust assays for identification of such inhibitors." (PMID 31105884, 2019).
cancer (continued). "Thus, the activated MEK/ERK pathway is required for elevated expression of UHRF1 and DNMT1 in these cancer cell lines." (PMID 30696879, 2019). "Notably, our co-expression analysis by database mining provides clear evidence for a widespread co-expression of UHRF1 and DNMT1 in normal tissues and numerous cancer cells." (PMID 30696879, 2019). "Nevertheless, it has also been suggested that impaired interaction between UHRF1 and DNMT1 could be the origin of the global hypomethylation in cancer cells." (PMID 31249594, 2019). "Thus, inhibition of either MEK1/2 or ERK1/2 down-regulated UHRF1 and DNMT1 expression in these cancer cells." (PMID 30696879, 2019). "Since UHRF1 and DNMT1 are co-expressed in different tissues and cancer cells and they are regulated at the transcription level by the MEK/ERK pathway, we hypothesized that they are co-regulated by a set of common transcription factors." (PMID 30696879, 2019). "Data mining reveals a marked co-expression of UHRF1 and DNMT1 in normal tissues as well as cancers." (PMID 30696879, 2019). "But unlike the case in mESCs, 2i regulates UHRF1/DNMT1 expression in cancer cells primarily at the level of transcription." (PMID 30696879, 2019). "The results summarized above suggest demethylation induced by UHRF1 depletion is not sufficient to fully open the chromatin structures of epigenetically silenced genes in cancer cells." (PMID 31064417, 2019). "Hence, any agent that decreases or suppresses the expression of UHRF1/DNMT1, as observed with natural anti-cancer drug, epigallocatechin-3-gallate (EGCG), will result in cell cycle G1/S arrest and apoptosis." (PMID 29932172, 2018). "In addition, UHRF1 binds to methylated promoters of many tumor suppressor genes by forming complexes with DNMTs and HDAC1, resulting ultimately in the formation of cancer." (PMID 28241740, 2017). "UHRF1 (ubiquitin-like, with PHD and RING finger domains 1) plays a crucial role in DNA methylation, chromatin remodeling and gene expression and is aberrantly upregulated in various types of human cancers." (PMID 28584306, 2017). "So far it is not yet clear why UHRF1 is up-regulated in cancer but some interesting leads are emerging." (PMID 28881702, 2017). "High UHRF1 levels are also attributed to downregulation of its epigenetic regulator H3K9 methyltransferase (G9a) in various cancers which works along with Yin Yang transcription factor 1 (YY1) as negative upstream regulator of UHRF1." (PMID 28881702, 2017). "It is tempting to speculate that there might be additional molecules acting upstream of UHRF1 to determine the methylation level of Rip3 promotor and RIP3 expression level among the cancer cells." (PMID 28981102, 2017). "Contrary to this expectation, however, our observation revealed that UHRF1 downregulation greatly leads to increasing the migratory and invasive properties of cancer cells rather than decreasing them." (PMID 28584306, 2017). "In addition, knockdown of epigenetic regulator UHRF1 (ubiquitin-like, containing PHD and RING finger domains 1) in RIP3-null cancer cells reduces the methylation level of the Rip3 promoter." (PMID 28981102, 2017). "Thus, UHRF1 plays an important role in HCC and is an attractive cancer target, although further validation is needed." (PMID 28060737, 2017). "UHRF1 is highly expressed in proliferating embryonic stem cells (HSCs) and a wide variety of proliferating cancer cells, but not in differentiated mature populations." (PMID 27738314, 2016). "Thus, both UHRF1 and UHRF2 negatively regulate de novo DNA methylation by targeting DNMT3A degradation in both normal somatic and cancer cells." (PMID 27462454, 2016). "Although UHRF2 is less frequently overexpressed in cancers in comparison with UHRF1 and is therefore less responsible for downregulation of DNMT3A in cancers, in a few cancer cell lines, especially A549, UHRF2 appears to play a dominant role in negative regulation of DNMT3A." (PMID 27462454, 2016).
cancer (continued). "Finally, we asked if the predicted regulators (UHRF1, WHSC1, and CBX7) influence DNAm at the same genomic loci across cancer types." (PMID 26169266, 2015). "Interestingly, UHRF1 also plays a role in recruiting HDAC1, which we also found consistently overexpressed in cancer, and which correlated specifically with DNA hypomethylation." (PMID 26169266, 2015). "UHRF1 expression was higher in certain types of the cancer tissues (12 tissues out of 16 tissues examined) than in normal tissues." (PMID 25765655, 2015). "Altogether, these observations show that immediately after DNA replication which generates hemi-methylated strands, UHRF1 is recruited with DNMT1 and/or likely DNMT3a and DNMT3b, in order to perpetuate gene repression, and particularly that of TSGs in cancer cells." (PMID 21496237, 2011). "An ideal property for future natural compounds as anti-cancer drugs, would be that cancer cells but not normal cells are affected by them in order to undergo apoptosis via an UHRF1 down-regulation." (PMID 21496237, 2011). "The analysis revealed that UHRF1 was not expressed in adjacent normal lungs, stromal cells, and invaded inflammatory cells, but was specifically expressed in the nuclei of cancer cells." (PMID 20517312, 2010). "There is some evidence to suggest that decreasing DNMT1 or UHRF1 in non-transformed cells can direct cells towards senescence, but whether this is also true in cancer cells, and the nature of the mechanisms involved, are unclear at present." (PMID 40595593, 2025). "This suggests that the development of UHRF1 inhibitors may be a promising strategy for inducing senescence without DNA damage in cancer cells." (PMID 40595593, 2025). "This likely explains why UHRF1 KO have not yet been reported in cancer cells." (PMID 38580649, 2024). "Our data supports a model in which UHRF1-dependent H3 ubiquitination ‘bookmarks’ genomic regions of low CpG density in late replicating chromatin for re-methylation by DNMT1, and that a disrupted UHRF1-DNMT1 ubiquitin signaling axis contributes to DNA hypomethylation in cancer." (PMID 39607687, 2024). "Therefore, we hypothesize that treatment with DNMT1 inhibitors may constitute an alternative to UHRF1 targeting and may be a potential therapeutic approach for treatment of KRAS-driven cancer." (PMID 37407562, 2023). "Since UHRF1 is highly expressed in cancer, while YAP signalling is known to trigger cancer initiation and growth of solid tumours, our study emphasises the possible benefits given by small compounds interventions targeting PIP4K as treatment for specific YAP-addicted cancer types." (PMID 36918565, 2023). "Thus, our work demonstrates that co-targeting of UHRF1 and KRAS may constitute a viable therapeutic approach for KRAS mutant cancers." (PMID 37407562, 2023). "However, UHRF2 is not functionally redundant in maintaining DNA methylation and, unlike UHRF1, the expression of UHRF2 in human cancers tends to be low due to mutation, copy number loss, or CpG hypermethylation of the promoter region." (PMID 36077796, 2022). "Although it seems that expressions of DNMT1, UHRF1, and DNMT3A are also upregulated in OXPHOS inhibition‐sensitive cancer cells identified in our screen, only DNMT1 expression exhibits a significantly positive correlation with cancer cell sensitivity to OXPHOS inhibition." (PMID 36382559, 2022). "The so-called “histone” modifiers are well-known to have non-histone substrates; similarly, UHRF1 may ubiquitinate and regulate unknown proteins relevant for its function in cancer." (PMID 35625988, 2022). "On the other hand, our analysis also showed hypomethylated DMPs for some genes, confirming previous reports showing that upregulated UHRF1/2 could mediate DNMT3A ubiquitination and proteasome-dependent degradation, leading to genome-wide de novo DNA methylation in cancer cells." (PMID 34294135, 2021).
cancer (continued). "This also suggest that TQ could be a promising epidrug that acts via a specific inhibition of UHRF1 expression levels in cancer cells without affecting its expression in normal human cells." (PMID 33922029, 2021). "Collectively, these studies identify UHRF1 as a selective reader of LIG1K126me2 in vitro and further implicate the histone and non-histone methyllysine reader activity of the UHRF1 TTD as a dispensable domain function for cancer cell DNA methylation maintenance." (PMID 33097091, 2020). "As our in vitro data showed LIG1K126me2 peptides bound the UHRF1 TTD with high affinity and selectivity, we next sought to determine whether this mode of interaction might be an approach to antagonize UHRF1 function in cancer cells." (PMID 33097091, 2020). "However, despite being functional in the same pathway and frequently overexpressed in cancers, it is not known if the expression of UHRF1 and DNMT1 is coordinately regulated and, if does, by what signaling pathway(s)." (PMID 30696879, 2019). "Moreover, a different line of evidence revealed that UHRF1 overexpression also acts as a negative regulator by degradation of the de novo DNA methylation protein, DNMT3A, as an additional mechanism leading to widespread DNA hypomethylation in cancer cells." (PMID 31249594, 2019). "Moreover, UHRF1, a well-documented regulator of gene expression in cancer, was downregulated by TIT3 suggesting that UHRF1 could be a potent target for TIT3 in HCC." (PMID 31482051, 2019). "UHRF1 (Ubiquitin-like containing PHD and RING finger domains 1) is one master regulator gene/protein in epigenetics which coordinates DNA methylation and histone modifications, which also mediates repair of damaged DNA that makes cancer cells resistant toward cytocidal drugs." (PMID 29932172, 2018). "Targeting of UHRF1 also decreased the migration and invasion of cancer cells by hampering endothelial to mesenchymal transition (EMT) as evidenced by up regulation of (EMT opposing) E-cadherin and down regulation of (EMT favoring) β-catenin, vimentin, N-cadherin and snail in UHRF1 knockdown cells." (PMID 28881702, 2017). "Indeed, overexpression of UHRF1 is maintained throughout the cell cycle in cancer cells but not in normal cells." (PMID 28881702, 2017). "In the Kaplan–Meier analysis, the UHRF1-positive group (n = 40) exhibited significantly poorer overall survival (OS) and cancer-specific survival (CSS) than the UHRF1-negative group (n = 120) (3-year OS rate 51.4% vs. 81.0%, log-rank P = 0.0023; 3-year CSS rate 59.1% vs. 85.1%, log-rank P = 0.0057)." (PMID 27507047, 2016). "CKS2 (chr9q22.2), CEP55(chr10q23.33), UHRF1 (chr19p13.3), RRM2 (chr2p25.1), AURKA (chr20q13.2), FLJ39632 (chr14q11.2), FAM83D (chr20q11.23), NEK2 (chr1q32.3) and MAD2L (chr4q27) were all located on PCSRs and showed over-expression in the 9, 8, 10, 9, 8, 9, 9, 8 and 9 types of cancers, respectively." (PMID 24796549, 2014). "The UHRF1 was stained specifically in the nuclei of cancer cells, but not in the other cells." (PMID 20517312, 2010). "Expression of UHRF1 was observed only in cancer cells, not in stromal cells." (PMID 19491893, 2009). "However, very few non-epigenetic roles of UHRF1 in cancer have been reported." (PMID 38725075, 2024). "Since UHRF1 and DNMT1 cooperate to maintain DNA methylation, we reasoned that the anthracycline derivative UHRF1 inhibitors identified here should induce DNA demethylation, and could have synergistic cancer cytotoxic activity with known DNMT inhibitors such as decitabine." (PMID 31105884, 2019).
cancer (continued). "This suggests that a therapeutically-induced inhibition of UHRF1 activity or expression could prevent the action of its preferred partners, HDAC1 and DNMT1, leading to a re-expression of the tumour suppressor genes p16INK4A and thus allowing the cancer cells to undergo apoptosis." (PMID 21496237, 2011). "None of the six genes (MMP11, ANGPTL1, GSTM5, IQGAP3, UHRF1, and CCBE1) have previously been categorized as carcinoma biomarkers collectively." (PMID 39596491, 2024). "We found that 2i broadly down-regulated both UHRF1 and DNMT1, the axis of DNA maintenance methylation, but not de novo enzyme DNMT3A, in various cancer cells." (PMID 30696879, 2019). "Together, these results suggest that, unlike UHRF1, UHRF2 negatively regulates DNA methylation in various human cancer cell lines." (PMID 27462454, 2016). "Collectively, these studies demonstrate that DNA methylation maintenance is a ubiquitin-regulated process involving (but not exclusive to) UHRF1 enzymatic activity and suggest that a disrupted UHRF1-DNMT1 ubiquitin signaling axis contributes to the development of PMDs in human cancers." (PMID 39607687, 2024). "How this occurs is not entirely clear; however, UHRF1 and the related protein UHRF2 seem to destabilize DNMT3A, which may account in part for the low DNA methylation level seen in cancer cells." (PMID 35625988, 2022). "To identify which of the 80 TSGs mediate the UHRF1 phenotype in KRAS mutant cancer cells, we designed a focused CRISPR library targeting those genes and used this library to perform a screen in Cas9-expressing A549 cells treated with either a non-targeting control sgRNA or an UHRF1-targeting sgRNA." (PMID 37407562, 2023). "However, we found the regulation of UHRF1 and DNMT1 in cancer cells by 2i is not universal." (PMID 30696879, 2019). "Considering that cancer cells usually divide faster than normal cells and that they have a more stable phenotype throughout successive mitosis, especially under in vitro culture conditions, one might imagine that the DNMT1/UHRF1 tandem is more efficient in cancer cells than non-cancerous cells." (PMID 30669400, 2019).